TGFB3 (transforming growth factor beta 3)
Diseases named in the same sentence as TGFB3 in open-access papers (continued):
Sharing a sentence is not in itself a finding about the gene and the disease.
prostate carcinoma (12 papers, 2009 to 2024). A carcinoma that arises from epithelial cells of the prostate gland. "Forty-one candidates were all down-regulated in the first cohort of them, SPOCK3, SPON1, PTN and TGFB3 were associated with the prognosis of prostate cancer patients." (PMID 29190897, 2017). "For example, the loss of FOXA1 increased the level of transforming growth factor-beta 3 (TGFβ3) and activated TGFβ signaling pathway in prostate cancer." (PMID 36012038, 2022). "AA prostate cancer patients also exhibited a higher level of TGFβ3 in blood sera compared to the CA cohort." (PMID 33996789, 2021). "On the contrary, genes whose loss/down-regulation was implicated in prostate cancer cell invasion, metastasis formation and worse prognosis (AR, IGF1, IGF2, TGFB3, SEMA3E) were down-regulated in NE-like versus AdenoPCa tumors." (PMID 32041153, 2020). "This equates to a false negative rate of 58.3% (7/12) and a false positive rate of 9.1% (2/22) for using the reposition of TGFB3 to detect low T stage prostate cancer." (PMID 31681438, 2019). "TGFB3 gene expression levels have been identified as a potential biomarker for prostate cancer, being expressed at lower levels in prostate cancer than normal tissue." (PMID 31681438, 2019). "We find that directional repositioning of SP100 and TGFB3 gene loci stratifies prostate cancers of differing Gleason scores." (PMID 31681438, 2019). "Although both SP100 and TGFB3 displayed differential positioning patterns between low and intermediate/high Gleason score cancer specimens, the sensitivity for subgrouping prostate cancers by Gleason score based on positioning patterns is low." (PMID 31681438, 2019). "There were 24 genes that had been reported correlating with prostate cancer, among which TGFB3, PTN, ID4 were widely studied." (PMID 29190897, 2017). "We found that SPOCK3, SPON1, PTN and TGFB3 were significantly correlated with the progression-free survival (PFS) status of prostate cancer patients." (PMID 29190897, 2017). "Additionally, increased expression of TGFβ3 was detected in AA-derived prostate cancer cell lines compared to CA-derived cell lines." (PMID 33996789, 2021). "Similarly, LMNA repositioned in 36.4% (4/11), SATB1 in 34.8% (8/23), and TGFB3 in 31.8% (7/22) of prostate cancer tissues." (PMID 31681438, 2019). "Positioning patterns for SP100 and TGFB3 by prostate cancer subgroups." (PMID 31681438, 2019). "PTN and TGFB3 were also found to influence the PFS of patients with prostate cancer." (PMID 29190897, 2017). "Even so, the false positive rates of detecting low Gleason score prostate cancers were low because the direction of repositioning for SP100 and TGFB3 was mostly specific to the subgroups." (PMID 31681438, 2019). "Four genes (SPOCK3, SPON1, PTN and TGFB3) and a micro-RNA were selected for exploring their potential roles in the progression of prostate cancer." (PMID 29190897, 2017). "Through the analysis of seven datasets (TCGA, GSE30521, GSE4602, GSE55945, GSE69223 GSE104131, and GSE200879), we identified two upregulated genes (AMACR and GCNT1) and seven downregulated genes (TGFB3, SRD5A2, PGM5, HOXD10, AOX1, HSPB6, and SNAI2) in prostate cancer compared to normal tissue." (PMID 38374143, 2024). "LMNA and SATB1 positioning patterns were not able to stratify prostate cancers by Gleason score and SP100, TGFB3 and SATB1 were not accurate markers of risk or aggressiveness of the cancer." (PMID 31681438, 2019). "Finally, we selected TGFB3 for further analysis since it repositioned in one of two low risk Gleason score 6 prostate cancers, but not in two prostate cancers of unknown Gleason score and TNM stage, representing a potential low-risk/indolent prostate cancer biomarker." (PMID 31681438, 2019). "Additionally, in prostate cancer, FOXF2 has an opposite regulatory effect with TGFβ3 pathways, which is described as triggering EMT via MMP-dependent mechanisms." (PMID 27487137, 2016).
prostate carcinoma (continued). "Interestingly, for SP100 and TGFB3 it was not the repositioning itself, but the direction of repositioning that was useful for stratification of prostate cancers." (PMID 31681438, 2019). "We find that SP100 and TGFB3 occupy alterative positions in low Gleason score cancers compared to higher Gleason scored cancers, and that LMNA repositions more internally in many non-metastatic and low risk prostate cancers, but infrequently reposition in high risk/aggressive cancers." (PMID 31681438, 2019). "TGFβ3 (transforming growth-factor β3) is expressed in BPH and normal prostate basal epithelial cells, but is reduced or absent in prostate cancer." (PMID 20027305, 2009).
ovarian carcinoma (11 papers, 2013 to 2024). A malignant neoplasm originating from the surface ovarian epithelium. "TGFB1 and TGFBR1 expression did not affect survival (data not shown), while TGFB2, TGFB3, TGFBR2, and TGBR3 overexpression decreased patient survival among ovarian cancer patients when the microarray data was assessed." (PMID 38196068, 2024).
colorectal cancer (10 papers, 2003 to 2025). A primary or metastatic malignant neoplasm that affects the colon or rectum. "Through down-regulating FOXA1 and up-regulating TGFB3, miR-93-5p in exosomes of tumor-associated fibroblasts enhances radiation resistance of colorectal cancer cells." (PMID 34130593, 2021). "Within the TGFb super family, TGFb1, TGFb2, and TGFb3 play roles in these oncogenic processes and elevated systemic TGFb levels have been found to be correlate to poor prognosis factor in colorectal cancer." (PMID 30728909, 2019). "To summarise, we have investigated the prognostic significance of the angiogenic marker CD105 and its ligands TGFβ1 and TGFβ3 in patients with colorectal cancer by immunohistochemistry and ELISAs." (PMID 12778073, 2003). "Similarly and more recently, TGFβ3 levels were obvious increased in plasma from patients with colorectal carcinoma, and TGFβ3 levels were significantly higher in preoperative than in postoperative plasma samples." (PMID 25401103, 2014). "TGFβ3 was detected in 79% (60 out of 76) of patients with colorectal cancer." (PMID 12778073, 2003). "In order to ascertain if this strong expression of CD105 in the tumour vasculature is reflected in patients' plasma, circulating levels of CD105, TGFβ1 and TGFβ3 together with the receptor–ligand complexes were quantified in patients with colorectal carcinoma and normal controls." (PMID 12778073, 2003). "Therefore, they proposed that TGFβ3 could act as a potential marker of angiogenesis, especially for colorectal carcinoma patients." (PMID 25401103, 2014). "While not fully characterized in colorectal cancer, inhibition of TGFβ3 in preclinical models of glioblastoma multiforme is associated with decreased expression of downstream SMAD oncogenes, decreased tumor invasiveness, and dampened TGFβ1/TGFβ2 signaling." (PMID 36382087, 2022). "In conclusion, this study demonstrates that MVD quantified using a Mab to CD105 is an independent prognostic parameter for survival of patients with colorectal cancer, and that plasma levels of CD105, TGFβ1, TGFβ3 and CD105/TGFβ complexes may be useful markers for assessing disease progression." (PMID 12778073, 2003). "Quantification of circulating CD105, its ligands TGFβ1 and TGFβ3 and the ligand–receptor complexes revealed elevated levels of CD105, TGFβ3, CD105/TGFβ3 and CD105/TGFβ1 complexes but not TGFβ1 in patients with colorectal cancer." (PMID 12778073, 2003).
glaucoma (10 papers, 2018 to 2024). Increased pressure in the eyeball due to obstruction of the outflow of aqueous humor. "We also found an increased expression of MMP-2, MMP-3, MMP-9, TGFβ-1, and TGFβ-3 in eyes with JIAU, independent of the presence of glaucoma." (PMID 29675026, 2018).
glioblastoma (10 papers, 2013 to 2024). The most malignant astrocytic tumor (WHO grade IV). "Recent studies assigning a dominant gatekeeper role for TGFβ3 in malignant glioblastoma progression, as well as specifically implicating TGFβ1 in breast and gastric cancers, support the continued pre-clinical and clinical investigation of these novel TGFβ antibodies." (PMID 30400822, 2018). "Also of interest, TGFb3 was recently described as a candidate gene for resistance of human glioblastoma multiforme cell lines to erlotinib, another tyrosine kinase inhibitor targeting EGFR." (PMID 23372733, 2013). "FAP expression correlated with TGFB1 and TGFB3, but not TGFB2 in all glioblastomas and in the mesenchymal subtype." (PMID 33494271, 2021).
keloid (9 papers, 2020 to 2024). An irregularly shaped, elevated mark on the skin caused by deposits of excessive amounts of collagen during wound healing. "The results showed that the expression of 12 genes (Hub genes) significantly increased in the development of keloid (P < 0.05) while that of TGFB3, SOX9, and BGN did not change significantly (P > 0.05)." (PMID 35872873, 2022). "Fibroblasts in keloids may specifically interact with macrophages and other MPs via TGFB2–TGFBR2, TGFB3– TGFBR3, CCL2-CCR1, and CCL2-CCR5 binding, which play inhibitory roles on the target cells." (PMID 35990663, 2022).
melanoma (9 papers, 2020 to 2024). A malignant, usually aggressive tumor composed of atypical, neoplastic melanocytes. "TGFB3 encodes transforming growth factor-β3 (TGF-β3), which is a multifunctional cytokine expressed in melanoma cells." (PMID 33428680, 2021). "The protein products of TGFβ-2 and TGFβ-3 are expressed only by neoplastic cells and participate in melanoma progression." (PMID 36899279, 2023). "In our control melanoma FTMs, TGFβ3 already showed a greater expression in the RF FTMs, indicating an intrinsically more activated TGFβ signaling in the RFs than in the PFs." (PMID 36232952, 2022). "The greatest level of B16 melanoma direct killing was seen in CD8+ T cells from animals treated with anti-TGFβ3 (47.8% killing), followed by those treated with anti-TGFβ1 (34.1% killing) and 1D11 (21.8% killing) compared to 10.6% killing in untreated controls." (PMID 34789823, 2021). "The association of upregulated TGFB3 gene expression and TGF-β signature with radiologic response was unexpected considering that activation of the TGF-β pathway normally leads to melanoma progression and metastasis." (PMID 33428680, 2021). "The TGFβ signature of CT26 colon carcinoma is defined by TGFβ1 and TGFβ1 inhibition results in tumor delay; B16 melanoma has equal expression of both isoforms and inhibition of either TGFβ1 or TGFβ3 controls tumor growth." (PMID 34789823, 2021). "For instance, avotermin, a recombinant TGFβ3 used in clinical trials for the prophylactic treatment of tissue scarring of the skin, could be tested for the treatment of melanoma patients." (PMID 38201651, 2024). "Using B16 mouse melanoma and CT26 colon carcinoma as models of stroma-poor tumors, we demonstrate that myeloid/dendritic cells are the main sources of TGFβ1 and TGFβ3." (PMID 34789823, 2021). "As reported in the literature, the mRNA transcript for TGFβ-2 is characteristic only for melanoma cells, while the transcripts for TGFβ-1 and TGFβ-3 - for normal and neoplastic cells." (PMID 36899279, 2023). "In this study, we characterized the immune cell expression of TGFβ1 and TGFβ3 in non-stromal rich tumors using mouse melanoma and colon carcinoma as model systems." (PMID 34789823, 2021). "Similarly, IL1B was expressed at much higher levels in iCAFs derived from melanoma, while TGFB3 and LGALS9 were strongly expressed in iCAFs from BCC and SCC but not melanoma." (PMID 39516494, 2024).
Obesity (9 papers, 2019 to 2025). Accumulation of substantial excess body fat. "By comparing regulators that were identified for lean, obese, and merged islet expression data, Cck, C1ql3, Serpina7, Creld2, Svop, Smoc1, Tgfβ3, and Serpini1 were identified to affect islet function in obesity." (PMID 31300714, 2019). "TGFβ3 was also proven to play an anti-inflammatory role and might participate in obesity and insulin resistance." (PMID 36425072, 2022). "TGFβ3 secretion was also found to be decreased in a genetic model of mice with CD4+ T cell-specific KLF10 knockout in vitro and in vivo, and these mice have a predisposition to obesity, insulin resistance, and fatty liver." (PMID 36425072, 2022). "Thus, consistent with Tgfβ3 expression in rodent tissue, TGFβ3 expression is greatly enhanced under conditions of obesity in visceral fat, suggesting that human TGFβ3 may display a similar time-of-day role in the proliferation of adipose tissue under lean conditions." (PMID 34108488, 2021).
osteoarthritis (9 papers, 2012 to 2025). A noninflammatory degenerative joint disease occurring chiefly in older persons, characterized by degeneration of the articular cartilage, hypertrophy of bone at the margins and changes in the synovial membrane. "Indeed, similarly to what was previously found for the osteoarthritis‐derived human chondrocytes (HACs), the supplementation with TGFβ3 and BMP7 combined dramatically improved ATDC5 chondrogenesis." (PMID 40415244, 2025).
fibrosis (8 papers, 2017 to 2026). the formation of excess fibrous connective tissue in an organ or tissue in a reparative or reactive process. "TGFB3 mutations result in dysregulated collagen matrix reorganization and fibrotic lesions associated with the ventricular fibrosis and aortic or mitral valve disease." (PMID 32456345, 2020).
glioma (8 papers, 2013 to 2025). A benign or malignant brain and spinal cord tumor that arises from glial cells (astrocytes, oligodendrocytes, ependymal cells). "It has also been extensively studied in gliomas, yet the specific interactions between TGFβ1, TGFβ2, and TGFβ3 isoforms in astrocytic tumors remain poorly understood." (PMID 40620718, 2025). "The Tgfb3, Il6, and Il23a genes were strongly expressed in DCs cocultured with dying glioma cells pulsed with PS-PDT or with MTX (positive control) compared with the control group." (PMID 36539408, 2022). "RelB knockdown cells displayed diminished RNA expression of the mesenchymal genes N-Cadherin/CDH2, SMAD2 and TGFβ3, as well as lower levels of YKL-40/CHI3L1, a biomarker of aggressive and recurrent gliomas that is very strongly associated with the mesenchymal glioma subtype." (PMID 23451236, 2013). "TGFB3 expression has also been detected in human glioma cells and depletion of TGFB3 mRNA using TGFB3-specific antisense oligonucleotides decreased the invasiveness of human glioma cells in vitro, but its role in pathobiology or prognosis of high-grade gliomas remains unknown." (PMID 36980562, 2023). "In the next part of the study, changes in the expression levels of TGFβ1, TGFβ2, TGFβ3, and ACTB were evaluated in gliomas with different degrees of malignancy." (PMID 35454784, 2022).
Marfan syndrome (8 papers, 2016 to 2025). A disorder of the connective tissue. "TGFB2 variants result in a phenotype overlapping with Marfan syndrome and are associated with thoracic aneurysms and mitral valve prolapse, while TGFB3 variants present with craniofacial anomalies, joint laxity, and aortic dilation." (PMID 40981152, 2025). "In the aortic tissue of patients with familial ATAA, Marfan syndrome, or patients who have mutations in TGFB2, TGFB3, TGFBR or SMAD3, increased TGFB signaling was reported." (PMID 37238945, 2023). "Mutations in MYLK cause a vascular disease that is different both from that in Marfan syndrome and from that associated with mutations that disrupt TGF-β signaling pathways (mutations in TGFβR1, TGFβR2, SMAD3, TGFβ2, TGFβ3)." (PMID 27586135, 2016). "Historically, the understanding of heritable TAAD was anchored in syndromic disorders such as Marfan syndrome (caused by pathogenic FBN1 variants) and LDS (linked to TGFBR1, TGFBR2, SMAD3, SMAD2, TGFB2, and TGFB3), conditions defined by clear Mendelian inheritance patterns and systemic features." (PMID 40981152, 2025). "Causative genes include autosomal polycystic kidney disease (PKD1, PKD2), Ehlers–Danlos syndrome (COL3A1), Marfan syndrome (FBN1), Loeys–Dietz syndrome (TGFB2, TGFB3, TGFBR1, TGFBR2, SMAD2, SMAD3), and Majewski Osteodysplastic Primordial Dwarfism (PCNT)." (PMID 40004483, 2025). "Furthermore, TGFB3 mutations in Loeys-Dietz Syndrome 5 (LDS5)/Rienhoff syndrome (RNHF) (OMIM#615582) are associated with connective tissue disorders and Marfan syndrome (MFS)-like features, including congenital heart defects (CHD), aortic aneurysms, and valvular disease." (PMID 32456345, 2020).
Myocardial fibrosis (8 papers, 2019 to 2026). "Thus, we treated human CFs with Ang II‐induced medium (100 nmol/L) for 24 hours to determine the relationship between myocardial fibrosis and TGFβ3." (PMID 30983140, 2019). "Therefore, we speculated that TGFβ3 might have protective effects against Ang II‐induced myocardial fibrosis." (PMID 30983140, 2019). "Thus, TGFβ3 might mediate the attenuating effect on CFs proliferation, ECM production and myocardial fibrosis, and promotion effect on collagen cross‐linking, which might provide a new understanding and TGFβ3‐based therapeutic strategy for myocardial remodelling." (PMID 30983140, 2019).
atherosclerosis (7 papers, 2018 to 2025). A disease characterized by the build-up of fatty material and calcium deposition in the arterial wall resulting in partial or complete occlusion of the arterial lumen. "The network with regulator NR3C1 was activated, inhibiting TGFB3, which is involved in the pathogenesis of atherosclerosis via TGF-β signaling." (PMID 35925965, 2022). "Unsupervised DEGs analysis of SMCs revealed increased expression in Abcb8ECKO of TGF-β-pathway genes such as Tgfb1, Tgfb2, Tgfb3, Mmp2 and Col1a1, inflammatory genes such as Ccl2 (encoding for MCP1) and Csf1 as well as atherosclerosis-associated genes including Egr1, Sqstm1, Irf1, Sox4 and Xylt1." (PMID 41252867, 2025).
cardiomyopathy (7 papers, 2020 to 2024). A disease of the heart muscle or myocardium proper. "These five pathogenetic HDV loci are associated with the susceptibility of osteopetrosis (CLCN7), hearing loss (GJB2), cardiomyopathy (PRDM16), arrhythmogenic right ventricular dysplasia 1 (TGFB3), and sucrase-isomaltase deficiency (SI), respectively." (PMID 38448908, 2024). "Finally, Tgfb3 (transforming growth factor, beta 3), included in the functional pathways of the Chagas, hypertrophic, diabetic, and dilated cardiomyopathies, would have also been neglected although CUT = 1.093 < x = 1.166." (PMID 38534766, 2024). "Since this increased TGFβ signaling seems compatible with the survival of Tgfb3+/− mice, it is possible that adult Tgfb3+/− mice will develop progressive cardiovascular disease such as aortic aneurysm, valvular heart disease, and cardiomyopathy." (PMID 32456345, 2020). "However, several genes that have been implicated in cardiomyopathy did demonstrate large differences between normal controls and HCM patients, including ANKRD1, FHL2, and TGFB3." (PMID 32344918, 2020). "The CTD database showed that the common hub genes (IGF1, MYH11, TGFB3, ALB, and AGT) were targets in cardiomyopathies." (PMID 35845066, 2022). "Among the identified DEGs, IGF1, MYH11, and TGFB3 had a high degree of interaction in the PPI network and were predicted to be key genes in cardiomyopathy." (PMID 35845066, 2022).